CDH2 (cadherin 2)
Diseases named in the same sentence as CDH2 in open-access papers (continued):
Sharing a sentence is not in itself a finding about the gene and the disease.
cancer (continued). "CDH2 mediates the trans-endothelial migration (TEM) of cancer cells by enhancing the endothelia attachment of circulating cancer cells." (PMID 34422665, 2021). "HHEX caused a repression of a series of neural stemness genes or/and genes promoting cancer, Sox1, Sox2, Myc, Cdh2, Vim, Hes1, Zic1, Pax6, Ezh2, and Lsd1." (PMID 34595169, 2021). "Western blot assays showed that the decreased CDH1 expression and enhanced mesenchymal (CDH2 and vimentin) and cancer stemness (CD44, ABCG2, OCT4 and MYC) marker expression were abolished after treating MCF-7OE-UBE2O cells with rapamycin." (PMID 31907353, 2020). "Dysregulated Wnt signaling is implicated in meningioma, and the CDH2 small molecule antagonist ADH-1 is both safe and effective at blocking N-cadherin-dependent cancer growth." (PMID 32968068, 2020). "qPCR analyses revealed that the mesenchymal markers (i.e. SNAI1, SNAI2, ZEB1, ZEB2, CDH2, vimentin and fibronectin) expression was decreased in cancer EVs-exposed BRCA1-KO fibroblasts, while the expression of CDH1 was increased." (PMID 31200749, 2019). "FLG interacts with MCL1, USP1, C21orf59, MAK, and KIR3DS1 and mucin interacts with ERBB3, SNAI1, TWIST1, TWIST2, and CDH2, all of which, IPA predicted to be associated with cancer." (PMID 31058088, 2019). "The loss of E-cadherin during the epithelial-mesenchymal transition in cancer is associated with a positive regulation of NCAM1 and CDH2." (PMID 31921388, 2019). "A list of significant biomarkers for cancer was generated like CDH2 and CDK7, and functional enrichment analysis identified the role of miRNAs in major pathways like cell adhesion molecules pathway affected by cancer." (PMID 29516011, 2018). "During EMT, the loss of E-cadherin is often accompanied by gain of N-cadherin (CDH2) expression, which provides new, more flexible cell-cell contacts that are compatible with cancer cell migration." (PMID 30463358, 2018). "In conclusion, our results suggested the important roles of ITGA2, FN1, ICAM1, TIMP1 and CDH2 in the progression of PTC via various cancer-related pathways." (PMID 30414611, 2018). "Some of the target genes were closely related to cancer development, such as CDH2, ZEB2, MAP3K2, and SLC24A4." (PMID 28298809, 2017). "Among these, N‐cadherin/CDH2, which is notable as a cancer cell protein that promotes metastasis, was highly downregulated in response to CCN1 silencing." (PMID 28694244, 2017). "CDH2 is typically expressed in mesenchymal cells and its upregulation in cancer promotes cell motility and invasiveness." (PMID 29206234, 2017). "Especially the shift from E-cadherin to N-cadherin (cadherin-2) expression correlates with cancer progression and metastasis." (PMID 26041890, 2015). "Differential gene expression analysis showed overexpression of classic epithelial genes (for example, SFTPC and STEAP1), genes associated with cancer (for example, CLDN6) and regulators of EMT (for example, VIM, FN 1 and CDH2) in Oncopig LC versus normal pig lung tissues." (PMID 41407936, 2026). "We integrated analyzed the function of P4HA3 among 33 types of cancers, and found that P4HA3 was associated with proliferation markers (PCNA and MKI67), EMT markers (VIM, TWIST1, SNAI1, SNAI2, FN1 and CDH2), extracellular matrix (ECM) markers (MMP9, MMP7, MMP2 and MMP14)." (PMID 39504328, 2024). "In vitro experiments presented the cancer-promoting role of CDH2 in NSCLC." (PMID 37205010, 2023). "In this study, we show that the Bin/amphiphysin/Rvs (BAR) domain protein pacsin 2 (protein kinase C and casein kinase substrate in neurons protein 2) plays an essential role in collective cell migration by regulating N-cadherin (also known as CDH2) endocytosis in human cancer cells." (PMID 37132654, 2023). "Additionally, we discuss microenvironment-driven treatment resistance and relapse, and elaborate the role of CDH2-mediated cancer cell protection from chemotherapy." (PMID 37132370, 2023).
cancer (continued). "In the majority of the 5 cancer types, PIK3CD expression was linked favorably with the expression of mesenchymal markers such as VIM (Vimentin), TWIST1, SNAI1 (SNAIL), SNAI2 (SLUG), and CDH2." (PMID 37861728, 2023). "Intriguingly, N-cadherin (also known as CDH2) was found among the genes that were the most upregulated in each of the Hela-CSRP2BP cells, and this gene is associated with EMT signalling and cancer metastasis." (PMID 37845756, 2023). "Similarly, no significant expression changes were observed in the studied mesenchymal markers in the resistant cancer cells such CDH2, VIM, ZEB1, ZEB2, SLUG, TWIST1 that which are upregulated in completed EMT." (PMID 35523936, 2022). "In contrast, ANGPTL2, BAG1, and CDH2 were mainly expressed in cancer cells and oligodendrocytes." (PMID 36291283, 2022). "All three cell lines expressed CDH2 with expression being lowest in the N-thy ori-3-1 compared with both cancer cell lines and with the highest level of expression being detected in the SW1736 cell line, but these differences in expression were not significant." (PMID 35118633, 2022). "This could partly explain why cadherin switching from CDH1 to CDH2 only occurs in 50% of cancer cells that the structural changes from the compact chromatin to the more open euchromatin might require more complex coordination." (PMID 35637517, 2022). "Cancer cells highly expressing CDH2 were identified in the ascites samples obtained at recurrence." (PMID 36553542, 2022). "This process occurs during cancer development, where there is a loss of expression of epithelial-associated molecules like CDH1 and an increase of mesenchymal-associated molecules such as N-cadherin (CDH2), vimentin (VIM), and fibronectin (FN1)." (PMID 34524579, 2022). "We study the role of CDH2 in niche-mediated cancer cell quiescence and proliferation." (PMID 35977468, 2022). "Moreover, previous studies have shown that downregulation of VCAM1, ICAM1, and CDH2 can inhibit cancer cell proliferation and migration." (PMID 34098960, 2021). "Since the circRNAs hsa_circ_0051620| SLC1A5 and hsa_circ_0066954| POLQ interact with CDH2, they might have a prognostic value in cancer." (PMID 34055888, 2021). "Importantly, there was a decrease in the expression of CDH2 which has been shown to be positively correlated with PAX2 activity, and is important in signalling stem cell differentiation and has been linked to cancer metastasis." (PMID 34722257, 2021). "The colocalized Cx43 and CDH2 in cancer cell lines were similar in 22 BM biopsies from BC patients." (PMID 34078741, 2021). "Moreover, CDH2, CP and TF were low expressed in primary cancer than normal tissues, but highly expressed in metastatic liver cancer." (PMID 34422629, 2021). "CDH2 gene upregulation in cancer cells also induces angiogenesis via modulating VEGF." (PMID 35178360, 2021). "Estrogenic induction of mesenchymal markers SNAI1, SNAI2, and CDH2 expression, with a consequent increase in cancer cell migration, was shown to depend on CXCR7, indicating a key role for CXCR7 in mediating estrogen upregulation of mesenchymal markers to induce invasion of OC cells." (PMID 30051594, 2018). "In addition, there were multiple genes induced that are involved with cell and organelle structure and function (PNCK, UBD, CDH2, HERC5) and importantly, genes associated with the prostate, AR (MMP7, CDH2, ENO2, IGFBP3) and cancer (IFIT3, IFI44L)." (PMID 29416764, 2018). "Quite interestingly, genes and associated interaction partners that were downregulated upon Hic-5 KD comprised members and/or associated partners of the TGFβ pathway (including TGF-β2, TGFβR, TGFβRII, FGF2, CTGF, FGFR, SRC, RUNX2 and CDH2), that are commonly implicated in inducing EMT in cancer." (PMID 29137281, 2017). "Many of the up-regulated transcripts are associated with cancer biology; e.g., ADAM19 and CDH2." (PMID 21789255, 2011).
cancer (continued). "Given that M2 macrophages are known to induce epithelial‐mesenchymal transformation (EMT) in cancer cells, we explored the correlation between VSIG4 and several biomarkers associated with EMT processes (MMP9, SNAI1, SNAI2, VIM, TWIST1, TWIST2, CDH1, CDH2) in CRC through the TIMER2.0 website." (PMID 40405491, 2025). "Interestingly, yarrow-Sep inhibited key lipid metabolic targets in CRC cells extensively shown to be implicated in cancer dissemination and prognosis —SREBF1, FASN, ABCA1 and HMGCR— and epithelial to mesenchymal targets—CDH1, ATP1B1, CDH2 and Vimentin—augmenting cell adhesion." (PMID 38576446, 2024). "In addition, we also analyzed the correlation between NUTF2 and the epithelial–mesenchymal transition (EMT) markers, Vimentin (VIM), TWIST1, Snail1 (SNAI1), Snail2 (SNAI2), Fibronectin 1 (FN1), and N‐cadherin (CDH2), which were widely accepted to be involved in cancer metastasis." (PMID 35155261, 2022). "Furthermore, targeting CDH2 may be an alternative or combination strategy to inhibit progression of ARTN dependent cancer." (PMID 34422665, 2021). "In addition, the interaction between cadherin 1 (CDH1) and cadherin 2 (CDH2) may also have some beneficial effect for cancer cell colonization." (PMID 31753020, 2019). "The spread of disease in many cancers has been linked to the expression of EMT transcription factors, which lead to an invasive phenotype characterized by low expression of epithelial marker E-cadherin (CDH1) and high expression of mesenchymal markers Vimentin (VIM) and N-cadherin (CDH2)." (PMID 25605241, 2015). "Analyses of primary cancers and cancer cell lines from different entities revealed an inverse relationship of ZEB1 and E-cadherin (encoded by the CDH1 gene) expression and a positive correlation between ZEB1 and N-cadherin (encoded by the CDH2 gene) expression." (PMID 23667256, 2013). "PTX‐resistant cancer cells were divided into PTX + EVs‐si‐NC, PTX + EVs‐si‐HOTAIR + oe‐NC, and PTX + EVs‐si‐HOTAIR + oe‐CDH2." (PMID 40235720, 2025). "For instance, CDH2 and CDH3 were found activating epithelial-to-mesenchymal transition (EMT) and Cell cycle cancer-related pathways in NSCLC." (PMID 40860670, 2025). "PTX‐resistant cancer cells were then divided into three groups: PTX + EVs‐si‐NC, PTX + EVs‐si‐HOTAIR + oe‐NC, and PTX + EVs‐si‐HOTAIR + oe‐CDH2." (PMID 40235720, 2025). "CDH2, ZEB2, SNAI2, and SNAI1 are important regulatory genes that increase the motility and invasion capacity of cancer cells." (PMID 41179704, 2025). "We also found five genes discovered by the consensus DEA and PCA and annotated as candidate cancer genes in NCG: AJAP1, CD1B, CDH2, PABPC4L, and PCDH10." (PMID 40788820, 2025). "In cancer, the CDH1-to-CDH2 switch stabilizes mesenchymal adhesion, directional migration, and anoikis resistance." (PMID 41462674, 2025). "Cadherin 2 (CDH2, N-cadherin) and cadherin 13 (CDH13, T-cadherin, H-cadherin) affect the progress and prognoses of many cancers." (PMID 39545598, 2024). "In addition, EMT is a crucial step of cancer cell migration and invasion, we focused on the possible associations between P4HA3 expression and classic EMT markers, such as Vimentin (VIM), TWIST1, Snail2 (SNAL2), Snail1 (SNAL1), Fibronectin1 (FN1), and N-cadherin (CDH2)." (PMID 39504328, 2024). "The JUN family and FOS family activities were up-regulated in the resistant cells, which had been proven to regulate E-cadherin (CDH1), N-cadherin (CDH2), and SNAIL2 expression in cancers." (PMID 39732719, 2024). "During the development of aggressive cancer, the epithelial-to-mesenchymal transition (EMT), characterized by a change in the expression from E-cadherin (CDH1) to N-cadherin (CDH2), enables cancer cells to acquire invasive and metastatic properties." (PMID 38675711, 2024).
cancer (continued). "A significant increase in CDH1 as well as significant decreases in CDH2 and MMP2 gene expression und s-μg indicated an induction of a mesenchymal–epithelial transition (MET) phenotype in the A549 cells, suppressing cancer progression." (PMID 38255998, 2024). "Pan‐cancer analysis of CAFs scores and EMT markers was performed, which revealed that fibroblast scores highly correlated with CDH2 (N‐cadherin), a mesenchymal marker." (PMID 36772945, 2023). "Conversely, CDH2 is frequently upregulated in OSCC, promoting a more aggressive behavior of cancer cells." (PMID 38067304, 2023). "The TEAD4/AP-1/SRC complex modulates a set of genes, including DOCKs (Dedicator of cytokinesis), CDH2 (Cadherin 2), and MACF1(Microtubule Actin Crosslinking Factor 1), to regulate cancer metastasis." (PMID 35602596, 2022). "We selected five genes (P57, CDK1, CDH2, E2F1 and BIK) that are quite relevant to cancer cell proliferation and apoptosis 24-28." (PMID 35371316, 2022). "The cadherin family, particularly N-cadherin (N-CAD; also known as CDH2), is critical for cell-cell adhesion and epithelial- mesenchymal transition (EMT) of cancer." (PMID 35574323, 2022). "One of the most important mechanisms in cancer metastasis is EMT occurring due to decrease in CDH1/E-cadherin levels and increase in CDH2/N-cadherin and VIM levels." (PMID 35317831, 2022). "When tumors promote cancer cell invasion and metastasis through the EMT pathway, CDH1 and Vimentin are often downregulated, while CDH2 is overexpressed." (PMID 35657638, 2022). "We also found strong correlations between MES and ADRN TFs with markers of cancer cell stemness and cancer cell motility including CDH1, CDH2, NANOG, SOX2, TWIST1, VIMENTIN, and Fibronectin across cancers." (PMID 35201514, 2021). "Another important aspect of TGF-β–induced EMT in cancer cells and in vitro epithelial cell EMT models is the cadherin switch, which is characterized by increased CDH2 (N-cadherin) expression and decreased CDH1 (E-cadherin) expression." (PMID 33792620, 2021). "Results show that SPARCL1, CDH2, CP, HP, TF and SERPINA5 were all significant downregulated in cancer tissues (p < 0.05)." (PMID 34422629, 2021). "The downregulated genes TNC and MMP1 are known to be commonly induced in cancer, the same is true for PMP2 and CDH2." (PMID 34439267, 2021). "CDH2 as an indicator of ongoing EMT and an increase of its expression has been correlated with the development of various types of carcinoma." (PMID 35008641, 2021). "Cadherin-2 (CADH2) plays a role in the epithelial-to-mesenchymal transition, which is the process considered to contribute to carcinoma progression." (PMID 32095334, 2020). "CDH2, a member of the cadherin superfamily, which is known as N-cadherin, is a mesenchymal cadherin involved in the EMT and metastasis of cancer cells." (PMID 31217907, 2019). "Altered expression profiles of epithelial E-cadherin (CDH1) and neuronal N-cadherin (CDH2) have often been observed in cancer cells, most notably in the context of the epithelial-to-mesenchymal transition (EMT) process that occurs during cancer progression." (PMID 31373305, 2019). "The top enriched disease and function pathways for the CDH1-specific and CDH2/CDH1-shared protein sets were cellular organization and cancer-related categories." (PMID 30630894, 2019). "The significant reduction in E-cadherin in CAOV3 and SKOV3 cells treated with TGF-β indicates its ability to switch cadherins (CDH1 to CDH2) and induce EMT which is essential for cancer invasion." (PMID 31336560, 2019). "N-cadherin (CDH2) functions to mediate cell–cell adhesion, it also plays a role in cancer metastasis." (PMID 29435142, 2018). "They used four established EMT markers—CDH1 (epithelial marker, E type), CDH2 (mesenchymal marker, M type), VIM (M type), and FN1 (M type)—as seeds to develop a pan-cancer EMT signature on the basis of TCGA pan-cancer RNA-Seq data." (PMID 29426364, 2018).
cancer (continued). "As with carcinoma, the epithelial marker CDH1 was downregulated in UM and down more in MetUM compared to the untransformed NUM, while the mesenchymal marker CDH2 was upregulated in UM and up more in MetUM." (PMID 28246385, 2017). "Epithelial Mesenchymal Transition (EMT) was another pathway depleted upon knockout, and subsequent analysis revealed a significant correlation between NNMT and EMT-related genes (VIM, CDH2, FN1, TGFB1, and ZEB2) in both the Cancer Cell Line Encyclopedia (CCLE) panel and patient data." (PMID 41997904, 2026). "Much less is known concerning the biological effects of other types of CDH2 antagonists, as they have not been extensively developed for use as cancer therapeutics (Ref." (PMID 37132370, 2023). "Interestingly, we also observed that the expression of CDH2, SPP1, TNC, CYR61, SERPINA1, and IL6 correlated with the progression of individual cancer stages." (PMID 37887075, 2023). "Non-peptide peptidomimetics of the CDH2 Trp-containing amino-terminus have also been discovered and are being developed as cancer therapeutics (Refs 38, 95)." (PMID 37132370, 2023). "In other words, high expression levels of CDH2/4/11 are crucial for the EMT and cancer metastasis." (PMID 36315446, 2022). "In late-stage cancer, cells seem to become resistant to its anti-mitotic effects and TGFB1 was instead observed to stimulate EMT by upregulating mesenchymal markers (e.g., VIM, CDH2) and downregulating epithelial markers (e.g., CDH1)." (PMID 35565214, 2022). "Further, our co-expression analysis also showed that key EMT-related factors such as MMP2, MMP9, CDH2, TGFB1, and VIM were highly expressed when CHN1 was highly expressed, while CDH1 was expressed at lower levels, suggestive of a potential cancer-promoting function of CHN1." (PMID 34152250, 2021). "Furthermore, Spearman correlation analysis in TCGA HCC tissues revealed that MARCH6 was positively correlated with MKI67, CTNNB1, CDH2, FN1 and WNTSA, which were demonstrated as oncogene in cancer growth and metastasis." (PMID 34273954, 2021). "Herein, the functional role of ARTN in CRC progression has been determined and demonstrated that ARTN promotes progression of CRC by p44/42 MAPK dependent expression of CADHERIN 2 (CDH2, also known as N-CADHERIN) which promotes epithelial-to-mesyenchymal transition and cancer cell metastasis." (PMID 34422665, 2021). "Furthermore, Twist1 expression positively correlates with EMT genes (CDH1, OCLN, TJP1, CDH2, FN1, SNAI1 and VIM) in various cancers." (PMID 32337580, 2020). "CDH2 is involved in the EMT process and promotes the growth and migration of cancer cells in LUAD." (PMID 33340396, 2020). "Loss of expression of E-cadherin (CDH1), and induction of expression of N- or R-cadherin (CDH2 or CDH4), triggers a series of events that allows cancer cells to become less dependent of their micro-environment, thereby promoting cell migration, invasion and metastasis." (PMID 29164272, 2018). "CDH2 (N-cadherin) is mostly expressed in the neuronal cells, and also involves in the process of epithelial-to-mesenchymal transition (EMT), which is correlated to the development of cancer stem cells (CSCs)." (PMID 28392805, 2017). "Furthermore, we found increased expression of EMT markers, including N-cadherin (CDH2), vimentin (VIM) and Snail (SNAL1), suggesting that B7-H3 may enhance the EGFR-ERK signaling pathway for cancer cell growth and metastasis." (PMID 38370387, 2024). "A small subset of mesenchymal genes (CDH2, DKK1, SERPINE2, MATN3, APLP1, CXCL1, FOXC2, BMP1) in Basal BRCA has been validated in this PRC2+-CGI pool with SERPINE2 and CXCL1 being the 2 most commonly overlapping genes found in 7 and 6 cancer types, respectively." (PMID 38902393, 2024).